BRCA2 (BRCA2 DNA repair associated)
Diseases named in the same sentence as BRCA2 in open-access papers (continued):
Sharing a sentence is not in itself a finding about the gene and the disease.
pancreatic cancer (417 papers, 2001 to 2026). "BRCA2 pathogenic mutations are well-established risk factors for breast, ovarian, prostate, and pancreatic cancers." (PMID 41769559, 2026). "Biopsy confirmed the diagnosis of pancreatic cancer, and germline testing revealed the coexistence of BRCA2 and PMS2 mutations." (PMID 40880847, 2025). "Because of this, BRCA1 and BRCA2 carriers have a well-established increased risk of multiple cancers, most notably, breast, ovarian, prostate and pancreatic cancers." (PMID 41256354, 2025). "Individuals with PGVs in BRCA1 or BRCA2 have a well-established increased risk of breast, ovarian, prostate, and pancreatic cancers." (PMID 39932614, 2025). "To analyse the mechanism of PARP inhibitor resistance in pancreatic cancer cells with BRCA2 deficiency, we developed olaparib and talazoparib resistant Capan‐1 cells." (PMID 40874518, 2025). "PARP inhibitors are currently FDA-approved for BRCA1- and BRCA2-mutated breast, ovarian, prostatic, and pancreatic tumors." (PMID 40842586, 2025). "BRCA1 and BRCA2 are key tumor suppressor genes involved in DNA repair, and their mutations significantly increase the risk of breast, ovarian, prostate, and pancreatic cancers." (PMID 40718262, 2025). "Since we found two patients that developed both melanoma and pancreatic cancer, we compared mutation landscape between the two tumors and identified a pathogenic variant in BRCA2 gene." (PMID 39609109, 2025). "Hereditary breast and ovarian cancer (HBOC) syndrome is primarily associated with mutations in BRCA1 and BRCA2, but increasing evidence links it to other malignancies, including male breast, prostate, and pancreatic cancers." (PMID 40649708, 2025). "Pancreatic cancer cells, such as Capan carrying a BRCA2 mutation and initially sensitive to PARP inhibitors, and the C2-2 clone derived from Capan and exhibiting resistance to PARP inhibitors, have been instrumental in studying PARP inhibitor resistance." (PMID 40308947, 2025). "BRCA2 mutations have been associated with increased risks of breast, ovarian, prostate, and pancreatic cancers." (PMID 39985003, 2025). "Preclinical studies have demonstrated that BRCA2-deficient pancreatic cancer cells are markedly more sensitive to the PARP inhibitor Talazoparib, both in vitro and in mouse xenograft models." (PMID 41155399, 2025). "BRCA1 and BRCA2 carriers have a well-established risk of multiple cancers including breast, ovarian, prostate and pancreatic cancers." (PMID 41256354, 2025). "Families with a causative gene linked to pancreatic cancer (eg, BRCA2 or yet undiscovered genes) and at least one case of pancreatic cancer in the family." (PMID 40180412, 2025). "Second, given the presence of the germline pathogenic BRCA2 variant, the patient was advised to undergo regular screenings for prostate and pancreatic cancers every 6–12 months." (PMID 39985003, 2025). "Pathogenic variants in the BRCA1 and BRCA2 genes increase the relative and absolute risks of developing breast, ovarian, prostate, and pancreatic cancer." (PMID 40772289, 2025). "Within familial pancreatic cancer, defined by the presence of two or more first-degree relatives affected with pancreatic cancer, BRCA2 mutations are discerned in about 5% to 10% of cases, and BRCA1 mutations are found in approximately 1%." (PMID 38809921, 2024).
pancreatic cancer (continued). "Only 29% (22/79) of websites (38%, 17/45 UKOs; 13%, 2/16 JCOs; 17%, 3/18 GTPs) provided information about BRCA1/BRCA2-associated male BC, prostate, pancreatic cancers, and/or melanoma risks." (PMID 39001386, 2024). "Two of the fifty-one genetically tested patients (4%) were BRCA2 mutation carriers, and both had first-degree relatives with pancreatic cancer." (PMID 39682288, 2024). "We treated a patient with advanced pancreatic cancer that bears a BRCA2 p.I3169M fs*48 germline variant." (PMID 37956396, 2024). "Individuals of both genders bearing harmful BRCA1 or BRCA2 variants face augmented risks of pancreatic cancer, albeit the degree of risk elevation is comparatively modest." (PMID 38809921, 2024). "A recent study on the molecular mechanism of BRCA mutations and CAF in pancreatic cancer reported enhancement of clusterin in BRCA1 or BRCA2 mutant CAF in a heat shock factor 1-dependent manner." (PMID 38182557, 2024). "Pathogenic BRCA1 or BRCA2 germline mutations contribute to hereditary breast, ovarian, prostate, and pancreatic cancer." (PMID 39198848, 2024). "Pancreatic cancer that bears germline BRCA2 p.I3169M fs*48 variant is sensitive to platinum and PARP inhibitors." (PMID 37956396, 2024). "Human pancreatic cancer cell lines resistant to PARPi demonstrated the expression of new BRCA2 isoforms resulting from the c.6174delT frameshift mutation." (PMID 38300310, 2024). "This is the first study to demonstrate synergistic interactions between PARPis (olaparib or talazoparib) and panobinostat, vorinostat, and decitabine in pancreatic cancer cell lines with wild-type BRCA1/2 (BxPC-3 or PL45) or BRCA2 mutation (Capan-1)." (PMID 38829622, 2024). "Individuals with pathogenic, or likely pathogenic, variants of BRCA1 and BRCA2 are at higher risk of breast, ovarian, and pancreatic cancers, and possibly other forms of cancer, too." (PMID 38730701, 2024). "The BRCA2 pathogenic variant has been associated with breast, ovarian, prostate, and pancreatic cancers, and melanoma." (PMID 39156267, 2024). "Both men and women with BRCA2 mutations also appear to have increased risks of gastric cancer, pancreatic cancer and melanoma." (PMID 38952711, 2024). "Mutations in the BRCA1 and BRCA2 genes are well-known risk factors for breast and ovarian cancer, but they also increase the risk of pancreatic cancer." (PMID 39409171, 2024). "The pathogenic BRCA2 variant c.4234_4236delACTinsC was detected in a family with pancreatic cancer and melanoma, with the proband being a female with pancreatic cancer." (PMID 39438962, 2024). "We were fortunate enough to get a few precious samples of pancreatic cancer tissue from the Icelandic Cancer Registry, from carriers of a founder mutation in BRCA2 that is quite common in Iceland, and were able to validate our findings." (PMID 39711301, 2024). "Based on the results of the POLO trial, patients with pancreatic carcinoma with germline loss-of-function BRCA2 mutations benefit from olaparib maintenance therapy following disease control with first-line oxaliplatin-based chemotherapy regimen." (PMID 38664720, 2024). "Compared with the ample data on PARP inhibitors in pancreatic cancers with germline BRCA1/BRCA2 mutations, data on cases with somatic mutations in the two genes are sparse." (PMID 36975505, 2023). "Pathogenic mutations in BRCA2 occur in 2% of patients with pancreatic cancer, and mutations in BRCA1 in 1% of patients." (PMID 36902416, 2023). "The mutation rates of BRCA1 and BRCA2 in familial pancreatic cancers are <1.2% and 5–17%, respectively, and those mutations increase the risk of disease by 2.26-fold and 3.5 to 10-fold." (PMID 37304241, 2023). "One additional patient displayed a somatic BRCA2 mutation in both the primary pancreatic tumor and BM." (PMID 38260832, 2023).
pancreatic cancer (continued). "In contrast, a benefit from PARP inhibitors in pancreatic cancer in other settings, such as somatic BRCA1/BRCA2 mutations, and in pancreatic cancers with mutations in non-BRCA1/BRCA2 DNA damage response (DDR)-associated genes is less clear." (PMID 36975505, 2023). "A BRCA2 pathogenic variant (p.Asp946Ilefs*14) was identified in a pancreatic cancer patient with a family history of abdominal cancer." (PMID 37951914, 2023). "Of these genes, BRCA1 and BRCA2 (BRCA1/2) are the most frequently investigated to assess their contribution to pancreatic cancer risk among Caucasians." (PMID 37951914, 2023). "Our findings emphasize the need for a better understanding of possible biological differences between pancreatic cancers that develop in patients with BRCA1 PVs vs BRCA2 PVs and consideration of stratification by mutation type in future clinical trials." (PMID 38010655, 2023). "PARP inhibitors are drugs that inhibit PARP enzymes and constitute the only targeted therapies used in pancreatic cancer indicated for tumors with germline BRCA1/BRCA2 mutations." (PMID 36975505, 2023). "Non-platinum alkylating agent mitomycin C has also been reported to possess efficacy in a few cases of metastatic pancreatic cancer patients with germline BRCA2 mutations refractory to platinum and olaparib, but prospective data do not exist." (PMID 36975505, 2023). "Capan‐1 is a human pancreatic cancer cell line that harbors a mutant BRCA2 with a frameshift mutation (6174 delT)." (PMID 36652375, 2023). "We found that BRCA2 deficiency increased autophagic flux, which was further enhanced by BET inhibition in Brca2-deficient pancreatic cancer cells, resulting in autophagy-dependent cell death." (PMID 37735513, 2023). "The simulated populations varied from general populations, to high‐risk groups (such as BRCA2 gene mutation carriers or kindreds of familial pancreatic cancer patients [FPC] or individuals with pancreatic cystic lesions), to PC patients." (PMID 36444505, 2023). "In a large cohort of patients with germline BRCA PVs and pancreatic cancer, BRCA2 PVs were associated with better outcomes compared with BRCA1 PVs." (PMID 38010655, 2023). "Germline BRCA1 and BRCA2 mutations (gBRCAm) can inform pancreatic cancer (PC) risk and treatment but most of the available information is derived from white patients." (PMID 36822114, 2023). "A cohort of 29 advanced pancreatic cancer patients with deleterious germline mutations in BRCA1/BRCA2 or PALB2 had longer OS (median OS 21.8 months versus 8.1 months) than matched controls without mutations." (PMID 36975505, 2023). "Mutations in BRCA1 and BRCA2 enhance tumor sensitivity to platinum-based chemotherapy in breast, ovarian, and pancreatic cancer." (PMID 36976649, 2023). "Further research revealed the role of BRCA2 germline mutations in developing ovarian, prostate, and pancreatic cancers." (PMID 37943872, 2023). "A benefit of maintenance olaparib versus placebo in prolonging PFS in first-line metastatic pancreatic cancer patients with germline BRCA1/BRCA2 mutations was observed in the Pancreas Cancer Olaparib Ongoing (POLO) phase III randomized double-blind trial." (PMID 36975505, 2023). "To identify novel vulnerabilities of BRCA2-deficient pancreatic cancer, we generated isogenic Brca2-deficient murine pancreatic cancer cell lines and performed high-throughput drug screens." (PMID 37735513, 2023). "Our data suggests that BET inhibition can be a novel therapeutic strategy for BRCA2-deficient pancreatic cancer." (PMID 37735513, 2023). "It is well known that carrying deleterious germline mutations in the BRCA1 and BRCA2 genes can increase the risk of developing pancreatic cancer." (PMID 37232812, 2023). "A BRCA2 protein-truncating pathogenic variant (p.Asp946Ilefs*14) was detected in an unselected pancreatic cancer patient, accounting for 0.7% (1/150) prevalence in the cohort." (PMID 37951914, 2023).
pancreatic cancer (continued). "In total, 63 different heterozygous variants were identified in BRCA1 (n = 27) and BRCA2 (n = 36) among unselected Pakistani pancreatic cancer patients." (PMID 37951914, 2023). "A neo-adjuvant chemotherapy study in patients with germline BRCA1/BRCA2 mutations and borderline resectable pancreatic cancer showed a complete pathologic response rate of 44.4%." (PMID 36975505, 2023). "Most of the clinical trials that involve molecular profiles of the pancreas tumour are those including patients with germline BRCA1/BRCA2 pathogenic variants." (PMID 36765737, 2023). "BRCA2 germline mutations are associated with an increased risk of breast, ovarian, and pancreas cancers." (PMID 36980614, 2023). "BRCA1/2 mutations have been identified in familial pancreatic cancers, with the majority being germline BRCA2 gene mutations, which occur in approximately 5–17% of patients with familial pancreatic cancer." (PMID 37035242, 2023). "Third, only two patients underwent germline genetic testing following the result of tumor sequencing because germline pathogenic BRCA1 and/or BRCA2 mutations are the only approved indication for targeted therapy in pancreatic cancer." (PMID 36463295, 2022). "We have previously shown that pancreatic cancers with BRCA2 mutations display notably increased susceptibility towards TRAIL receptor-stimulating agents." (PMID 36358659, 2022). "Germline heterozygous mutations affecting BRCA2 also significantly elevate the risk of cancers of the pancreas, male breast, prostate, and other tissues." (PMID 35494038, 2022). "BRCA2 pathogenic variant is usually associated with other cancers such as melanoma, prostate, and pancreatic cancers." (PMID 36230639, 2022). "Pathogenic mutations in BRCA1 and BRCA2 are associated with an increased risk of developing breast, prostate, and pancreatic cancer, as well as other cancers, among men and women." (PMID 35303741, 2022). "Mutations in the BRCA2 gene predispose patients to breast and ovarian cancer and confer a relative risk from 3.0 to 9.0 to develop pancreatic cancer." (PMID 35884779, 2022). "We have previously shown that pancreatic cancer with BRCA2 mutations exhibits a remarkably enhanced sensitivity towards tumor-necrosis-factor-related apoptosis-inducing ligand (TRAIL) receptor-stimulating agents." (PMID 36358659, 2022). "The BRCA2 mutation status seems to be dispensable for the effect of FBP1 on the sensitivity of pancreatic cancer to Olaparib." (PMID 34854226, 2022). "BRCA1 and BRCA2 PVs can be found in up to nearly 5% of the primary tumors of pancreatic cancer, with the highest frequencies in cohorts enriched for high-risk pancreatic cancer cohorts enriched for familiar cases." (PMID 35563100, 2022). "In 6,902 men with BRCA1 or BRCA2 mutations who developed cancer, especially breast, prostate, and pancreatic cancer, and multiple primary tumors, there was an association with a higher rate of BRCA2 mutations." (PMID 35251954, 2022). "Which cancer types and their clinical characteristics are associated with pathogenic variants in BRCA1 and BRCA2 in addition to breast, ovarian, prostate, and pancreatic cancers?" (PMID 35420638, 2022). "Particularly, germline BRCA2 mutations have been associated with an increased risk of pancreatic cancer (RR = 3.51; 95% CI = 1.87–6.58)." (PMID 35626055, 2022). "BRCA2 mutations are seen in about 6% in sporadic and up to 17% in familial pancreatic cancer, with an even higher incidence in the Ashkenazi Jewish population." (PMID 35228986, 2022). "Using CAPAN1 cells, a pancreatic cancer cell line harboring mutant BRCA2, it was previously shown that cisplatin selection can promote secondary mutations that lead to a restoration of the BRCA2 reading frame and subsequent resistance to cisplatin and PARPi." (PMID 36568963, 2022). "BRCA1 also increases the relative risk (RR) for pancreatic cancer by 2 to 4-fold, where BRCA2 increases RR by 3 to 8-fold." (PMID 35813042, 2022).
pancreatic cancer (continued). "While both BRCA1 and BRCA2 mutations have been extensively studied relative to pancreatic cancer risk, these screening studies have also demonstrated a higher prevalence of IPMNs in patients with BRCA mutations." (PMID 35884779, 2022). "Mutations in BRCA1 and BRCA2 genes are often found in breast cancer patients, and approximately 5% of pancreatic cancer patients also have mutations in these genes." (PMID 36291766, 2022). "Cell viability results from KPC BRCA2-proficient murine pancreatic tumor cells and BRCA2-deficient KPB tumor cells confirmed higher cytotoxicity of Niraparib in pancreatic cancer regardless of BRCA status." (PMID 36324587, 2022). "Previous trials have shown the positive effects of PARP inhibitors in breast and ovarian cancer patients involving BRCA1 or BRCA2 mutations, with similar findings in pancreatic cancer patients." (PMID 36291766, 2022). "Hereditary breast–ovarian cancer syndrome, attributed to BRCA1 or BRCA2 mutations, is also associated with increased risk of developing pancreatic cancer." (PMID 36500723, 2022). "Poly (ADP-ribose) polymerase (PARP) inhibitors have been approved in malignancies associated with germline BRCA1 or BRCA2 pathogenic variants, such as breast, ovarian, prostate, and pancreatic cancer." (PMID 36577523, 2022). "Another phase 2, open-label study assessed the efficacy and safety of olaparib in 23 advanced pancreatic cancer patients with confirmed genetic BRCA1 or BRCA2 mutations (NCT01078662)." (PMID 35228986, 2022). "The role of BRCA2 in FPC was evaluated using murine models of pancreatic cancer associated with Brca2 inactivation." (PMID 35163129, 2022). "Approximately 0.7%–5.7% and 0.3%–2.3% of unselected cases of pancreatic adenocarcinoma are linked to pathogenic mutations, respectively, in BRCA1 and BRCA2 genes, making them the most common cause of familial pancreatic cancer." (PMID 36307994, 2022). "For example, BRCA1 mutations in breast and pancreatic cancer are associated with increased density of tumor-associated macrophages (TAMs) and T cells, as compared to wildtype tumors and BRCA2 mutant tumors." (PMID 34572943, 2021). "The biological impact of BRCA1 and BRCA2 mutations are histology-dependent, in that they are indispensable founding events in some tumors (e.g., breast, ovarian, prostate and pancreatic cancer) and inert in others." (PMID 34572943, 2021). "A family history of pancreatic cancer is reported in about 5%–10% of newly diagnosed cases with germline mutations in BRCA2 contributing to approximately 6%–17% of these cases." (PMID 34707985, 2021). "BRCA1 or BRCA2 germline mutations reportedly increase the relative risk of pancreatic cancer by 2.26-fold (1.26−4.06) and 3.51-fold (1.87−6.58), respectively." (PMID 33562094, 2021). "Further, in mouse models of pancreatic cancer, BRCA2 mutations are associated with an immune ‘desert’ phenotype, while PALB2 mutant models show intermediate infiltration by immune cells." (PMID 34572943, 2021). "The BARD1 c.1333G>T variant occurred with BRCA2 c.1658T>G (p.Leu553Ter) in early onset TNBC women diagnosed with pancreatic cancer at the age of 32." (PMID 34646395, 2021). "Heterozygous and homozygous Brca2 loss significantly reduced pancreatic cancer-free survival (p < 0.0001), with the strongest effect seen in the homozygous-loss mice." (PMID 34712667, 2021). "Simon was also found to have the BRCA2 variant and discussed his increased risk of prostate and pancreatic cancer with a genetic counsellor at the time." (PMID 34649841, 2021). "Germline mutations in the BRCA2 gene are known to be highly associated with the risk of diagnosis with breast, ovarian, prostate, and pancreatic cancer." (PMID 35052422, 2021). "BRCA2 germline mutations significantly increase risk for prostate and pancreatic cancer and cause hereditary breast and ovarian cancer syndrome (HBOC)." (PMID 34283091, 2021).